OTOR (otoraplin)
Synonyms: FDP; MIAL; MIAL1
Tractability: Antibody: UniProt places it where antibodies can reach, with high confidence; UniProt predicts a signal peptide or a membrane-spanning region; its Gene Ontology location is reachable by antibodies, with medium confidence.
Gene: Protein-coding gene on chromosome 20 (16,748,358 to 16,770,062, forward strand). Ensembl gene ENSG00000125879.
Subcellular location: Secreted
Gene Ontology:
Molecular function: protein binding
Biological process: cartilage condensation; sensory perception of sound
Cellular component: extracellular region
Genetic constraint (gnomAD): Loss-of-function variants: 9 observed, 8.9 expected, observed/expected ratio (o/e) 1.01, 90% interval 0.61 to 1.7. That is too few expected variants to judge how well the gene tolerates losing a copy. Missense variants: 105 observed, 89.43 expected, observed/expected ratio (o/e) 1.17, 90% interval 1 to 1.38. Synonymous variants: 29 observed, 31.46 expected, observed/expected ratio (o/e) 0.92, 90% interval 0.69 to 1.26.
Homologues: Orthologues: chimpanzee OTOR (100% identical), macaque OTOR (98% identical), dog OTOR (91% identical), mouse Otor (87% identical), rat Otor (87% identical), guinea pig OTOR (85% identical), rabbit OTOR (83% identical), tropical clawed frog otor (51% identical), Drosophila melanogaster Tango1 (22% identical). Paralogues in human: MIA (42% identical), MIA3 (38% identical), MIA2 (37% identical), CTAGE1 (9% identical), CTAGE15 (8% identical), CTAGE6 (8% identical), SPZ1 (8% identical), CTAGE4 (7% identical), CTAGE8 (7% identical), CTAGE9 (7% identical).
Diseases named in the same sentence as OTOR in open-access papers:
OTOR is named in the same sentence as 6 diseases in open-access papers, as found by Europe PMC text mining. Sharing a sentence is not in itself a finding about the gene and the disease. The quoted sentences say what the papers report.
melanoma (4 papers, 2016 to 2023). A malignant, usually aggressive tumor composed of atypical, neoplastic melanocytes. "OTOR (melanoma inhibitory activity-like (alias MIAL)) may play a role in the development and maintenance of the inner ear." (PMID 37626864, 2023). "OTOR (otoraplin or MIAL1) and MIA belong to several extracellular SH3DCPs of the melanoma-inhibiting activity (MIA) family, and they contain only one SH3 domain." (PMID 37626864, 2023). "We also identified 2 differentially expressed genes from the melanoma inhibitory activity (MIA) family: MIA and otoraplin (OTOR)." (PMID 28974924, 2018). "The melanoma inhibitory activity (MIA) gene family includes MIA, MIA2, Transport and Golgi organization protein 1 (TANGO), and otoraplin (OTOR)." (PMID 27145272, 2016).
breast carcinoma (2 papers, 2022 to 2024). "OTOR promotes tumour growth in breast cancer by regulating mitogen-activated protein kinase/extracellular signal-regulating kinase-extracellular signal-regulating kinase (MEK-ERK) signalling." (PMID 37948019, 2024). "Besides, some studies have demonstrated that OTOR, HOXD3, and PEG10 were associated with prognosis in breast cancer." (PMID 35950033, 2022).
OTOR also shares sentences with these, for which no sentence is quoted: infection (2 papers); coagulopathy (1); deafness (1); tumour (1).